IRF3 (interferon regulatory factor 3)
Diseases named in the same sentence as IRF3 in open-access papers (continued):
Sharing a sentence is not in itself a finding about the gene and the disease.
infection (continued). "Sendai virus-induced IRF3 and TBK1 phosphorylation were dramatically reduced in MIB1/MIB2 double deficient MEFs compared to control mib1f/f MEFs in early infection." (PMID 23028469, 2012). "Similar to the immunoblot analysis, infection by the virus that expresses the wt ESEV protein resulted in an increase in nuclear localized IRF3 relative to that seen with infection by the ESEA virus." (PMID 22911767, 2012). "Infection with SeV translocated IFN-regulatory factor 3 (IRF-3), a transcription factor critical for efficient IFNβ induction, to the nucleus." (PMID 22272257, 2012). "A MAVS-dependent signal is thus induced upon infection with MVA orMVAΔF1L, which causes the IRF-3-dependent up-regulation of Noxa and apoptosis." (PMID 21698224, 2011). "Immunofluorescent staining revealed that in contrast to the late time point of infection in control MEFs, where IRF3 was observed in the nucleus of greater than 95% cells, PI-MEFs display nuclear IRF3 signal in only about 40% of the cells." (PMID 21677781, 2011). "These ISGs included Ifna2, Ifna4, and Ifnb1, which were induced to high levels in all four strains at 12 hours (>1000-fold) and 24 hours (>100-fold) post-infection, and likely represent early IRF3-mediated gene expression." (PMID 21379341, 2011). "Simultaneously or sequentially targeting TBK1 and IRF3 would be beneficial to MHV-A59 in spreading infection through effectively suppressing the type I IFN response." (PMID 21364999, 2011). "At 24 hrs post-infection, IRF3 was observed in the nucleus of most cells despite a significantly reduced level of expression." (PMID 21677781, 2011). "At 6 hrs post-SeV infection, a significant fraction of MEFs (∼40%) displayed strong IRF3 signals in the nucleus and the number of cells in which this was the case increased over time despite the decrease in the total level of IRF3." (PMID 21677781, 2011). "Noxa protein was induced during infection, and the induction of Noxa protein and apoptosis induction required transcription factor IRF3 and type I interferon signalling." (PMID 21698224, 2011). "Only a slight decrease in IRF7 protein was observed 24 hr post-infection, in contrast to the major degradation of IRF3." (PMID 21677781, 2011). "This other VZV protein should also be a tegument protein since VZV-mediated IRF3 phosphorylation happens very early after infection." (PMID 21347389, 2011). "In VZV-infected cells a slower-migrating form of IRF3 appears as soon as 4 hours post-infection (hpi) (lane 5) and accumulates over time, being still present at 32 hpi (lane 8)." (PMID 21347389, 2011). "The only common conclusion we can draw in comparison with the work of Sen and co-workers is the inhibition of the IRF3 pathway following infection with VZV." (PMID 21347389, 2011). "In conclusion, HCV recruits PKR early in infection as a sensor to trigger induction of several IRF3-dependent genes." (PMID 22022264, 2011). "The reduced fraction of cells in which IRF3 is in the nucleus in PI-MEFs compared to 24 hrs after initial infection suggests that some of the nuclear IRF3 was either degraded or exported during the establishment of persistent infection." (PMID 21677781, 2011). "Later in infection (when activated IRF-3 dimers are found in larger amounts) IRF-3 can perform this function by itself, and the requirement for NF-κB is obviated." (PMID 22022260, 2011). "Here, we showed for the first time that, following infection with VZV, an IRF3 slower-migrating form appears as soon as 4 hours post-infection and accumulates over time." (PMID 21347389, 2011). "Taken together, these data provide evidences that the viral kinase ORF47p, but not ORF66p, plays an important role in the phosphorylation of IRF3 following infection with VZV." (PMID 21347389, 2011). "Cells were harvested at various times post-infection and IRF3 homodimerization was monitored by native PAGE." (PMID 21347389, 2011).
infection (continued). "Eight and 24 hours post-infection, mDCs were collected, total cell extracts were performed and IRF3 up-shift was analyzed by SDS-PAGE." (PMID 21347389, 2011). "The participation of IRF3 was further confirmed by immunofluorescence studies which showed its nuclear translocation at 6 hours post-infection." (PMID 22022264, 2011). "Cells were sorted and infected with Ad5/3-Delta24 and four and 24 hours following infection, mRNA was collected and analyzed for type I interferons (IFNα and IFNβ) interferon regulatory factors IRF3, IRF7 and transcription factor STAT1 expression." (PMID 21079774, 2010). "As SeV induces the proteasome-mediated degradation of IRF3 at late times post-infection, it is likely that these differences stem from the model systems used." (PMID 20454685, 2010). "Collectively, the data presented herein demonstrate that IRF3 is activated upon infection with WT HSV-1." (PMID 20454685, 2010). "Similar effects on IRF3 localization were observed following infection of two additional human primary fibroblasts cells (MRC-5 and BJ; data not shown)." (PMID 20454685, 2010). "In our current study, however, we observed activation of endogenous IRF3 during the early stages of infection with WT HSV-1 in human fibroblasts." (PMID 20454685, 2010). "Significantly reduced responses to ΔTcpC were only observed from day five post-infection in Irf3−/− mice, showing that the response kinetics differed from wt mice." (PMID 20886104, 2010). "Taken together, both PML and IRF3 likely play a role in limiting HSV-1 infection but they appear to act at different times during the course of infection, and in turn, HSV-1 counters these respective responses accordingly." (PMID 20454685, 2010). "Abscess formation was also more extensive in Irf3−/− than in wt mice (day 7 post-infection, p<0.001)." (PMID 20886096, 2010). "The weak staining of IRF3 following D8 infection is consistent with studies suggesting that antibody detection of IRF3 favors its activated forms." (PMID 20454685, 2010). "The sustained IRF3 activation observed following either ICP0-null or R7914 infections correlated with ISG56 production." (PMID 20454685, 2010). "In contrast, the expression levels of IRF-3 remained the same except at 5 days after infection, where an average 26% reduction in IRF-3 expression was found." (PMID 19404407, 2009). "Results from our laboratory and others have shown that NSP1 from several different rotavirus strains targets IRF3 for proteasome degradation early post-infection." (PMID 19180189, 2009). "Reduction in IFN-I production that resulted from IRF3, IRF7, IFNβ or IFNAR deficiency by and large reflected the increase in resistance to lethal infection." (PMID 19325882, 2009). "Infection of rSeVhP in murine cells, however, strongly activates IRF-3 and NFκ-B, resulting in an increased level of IFN-β production compared with wt SeV." (PMID 21994561, 2009). "Possibly the much larger rate of cytoplasmic infection of macrophages drives IRF3-dependent IFNβ synthesis much more efficiently." (PMID 19325882, 2009). "A feed-forward amplification mode is characterized by IRF3-dependent IFNβ production that predominates the early phase of infection." (PMID 19325882, 2009). "The enhanced IRF-3 phosphorylation was paralleled by a significant increase in nuclear translocation, also observed at all time points of rhMPV-ΔG infection, compared to rhMPV-WT." (PMID 18516301, 2008). "IRF-3 phosphorylation occurred earlier and was significantly higher in rhMPV-ΔG infected cells at all time points of infection, compared to rhMPV-WT, which induced IRF-3 phosphorylation only at 15 and 24 h p.i.." (PMID 18516301, 2008). "For example, 2.5-fold higher levels of IFN activity were observed in IRF-3−/− mice at 48 h after infection (p < 0.0001)." (PMID 17676997, 2007).
infection (continued). "IRF-3−/− mice were uniformly vulnerable to infection and developed elevated WNV burdens in peripheral and central nervous system tissues, though peripheral IFN responses were largely normal." (PMID 17676997, 2007). "Mice deficient in IRF-3 showed increased WNV burden in the brain and spinal cord after peripheral infection." (PMID 17676997, 2007). "Although cell culture studies suggest that IRF-3 promotes antiviral control by inducing interferon (IFN)-β, near normal levels of IFN-α and IFN-β were observed in IRF-3−/− mice after infection by several RNA and DNA viruses." (PMID 17676997, 2007). "Moreover, hu-hnRNPM knockdown decreased IRF3 protein levels at 0, 4, and 8 h post-infection and reduced the phosphorylation of IRF3 induced by IAV infection at 8 and 12 h." (PMID 40434105, 2025). "Clearly, stringent regulation of the IRF3 and NF‐κB pathways is critical to prevent tissue damage during infection as evidenced by the orthogonal mechanisms multiple DEAD/H‐box helicases utilize to finely tune the activation and function of these transcription factors." (PMID 39620586, 2025). "To determine whether the IFN mRNA expression induced by TBK1 and IRF3 activation early in infection is regulated by RIG-I, we measured the effects of knocking out RIG-I." (PMID 39601535, 2025). "It is conceivable that during early-stage H. pylori infection, activation of the organism’s stress response triggers IRF3 activation, whereas prolonged infection stimuli may downregulate IRF3 expression, thereby fostering the occurrence of DSB." (PMID 39924917, 2025). "Among them, the most widely studied function is to regulate type I interferon in anti-infection immunity; e.g., African swine fever virus E120R protein interacted with host cell IRF3 to block the production of beta interferon and then inhibit the host’s antiviral immunity." (PMID 40488465, 2025). "A parallel increase in renal c-MYC protein levels was detected in tissue sections from infected Irf3−/− mice, compared to uninfected controls, specifically along the mucosal lining of the renal pelvis and in the renal papillae, which are primary infection sites." (PMID 40000737, 2025). "Consequently, the association of TBK1 and IRF3, which plays a vital role in type I interferon (IFN-I) induction, was blocked by EBOV trVLPs infection." (PMID 38285487, 2024). "We retrieved lists of the known targets of NF-kB/p65, STAT1, STAT2, IRF2, and IRF3 and extracted from these lists genes that were differentially expressed either during infection in Dicer WT or Dicer N1 cells, or between mock-infected Dicer WT and Dicer N1 cells." (PMID 38287188, 2024). "Particularly, irf3 FC values were 47.59 and 26.43 at 3 and 7 days after infection with DlNNV, respectively; these values were significantly lower (p < 0.05) than those reported in fish injected with the reassortant isolate (78.45 and 74.40 mean FC values at 3 and 7 dpi, respectively)." (PMID 38921776, 2024). "Regarding the IFN-I system-related genes, irf3 and rtp3 transcription was up-regulated following the infection with both viruses, although differences regarding the intensity and/or the temporal profile of the induction were observed when the results from both experimental groups were compared." (PMID 38921776, 2024). "One part of the infection response in various cell types is IRF3." (PMID 39861077, 2024). "As MAVS was not completely degraded until 12 h p.i., the remaining MAVS present early in infection (4 and 8 h p.i.)might account for IRF3 phosphorylation in cells infected with NSP1 mutant virus (rSA11-NSP1-35TAA)." (PMID 37905816, 2023). "However, activation of TBK1 and IRF3 during EV-A71 infection was suppressed when STING was silenced." (PMID 36823147, 2023). "Similarly, GPB2 and STAT2 transcription were induced more in IRF3-transfected cells during OC43 infection." (PMID 37197656, 2023).
infection (continued). "Moreover, transcription of the IRF3-dependent genes Ifit3 and Rsad2 was significantly increased upon infection with MCMV M35stop compared to MCMV REV." (PMID 37289084, 2023). "VP24, which is required for HSV’s viral capsid, can affect IFN-B production and block IRF3 activation by stopping the interaction between Tank binding kinase 1 (TBK1) and interferon regulatory factor 3 (IRF3) during infection, leading to the suppression of IFN expression." (PMID 38005873, 2023). "However, we found that the expression of IFN-β was upregulated in the CNS of Irf7−/− Ifnβ+/Δluc mice 7 days post-infection compared to WT Ifnβ+/Δluc and Irf3−/− Ifnβ+/Δluc animals." (PMID 37737190, 2023). "Our study identifies a new negative regulator of IRF3 activation, which might have potential significance in the control of infection and inflammation." (PMID 37673879, 2023). "In addition, both TBK1 (phosphorylated at Ser172) and IRF3 (phosphorylated at Ser386) were activated in THP-1 cells after EV-A71 infection." (PMID 36823147, 2023). "We first utilized a mouse model to evaluate the roles of TBK1 and IRF3 during EV-A71 infection." (PMID 36626364, 2023). "To clarify how IRFs demonstrate different antiviral effects against human coronavirus infection, we investigate expression levels of antiviral genes in cells transfected with control pcDNA3, IRF1-pcDNA3, IRF3-pcDNA3 or IRF7-pcDNA3 at 24 hours after infection of 229E or OC43." (PMID 37197656, 2023). "Moreover, we observed that wild-type TBK1, but not its mutants Y591F and Y591E, increased levels of phosphorylated IRF3 and Ifnb1 production induced by HSV1-GFP infection when PTK2B was co-expressed in TBK1-deficient MEF cells." (PMID 37989995, 2023). "We used Western blots to evaluate the levels of phosphorylated IRF3 (P-IRF3) after infection of cancer cells to assess whether the B2R deletion affects IRF3 pathway activation in the context of oncolytic VACV infection." (PMID 37016144, 2023). "Therefore, it is worth pinpointing the roles of IRF3 and AP-1 in surviving harsh immune responses during infection." (PMID 38084936, 2023). "Deletion of DDX50 in mouse and human cells impaired IRF3 phosphorylation and IRF3-dependent endogenous gene expression and cytokine/chemokine production in response to cytoplasmic dsRNA (polyIC transfection), and infection by RNA and DNA viruses." (PMID 35215908, 2022). "Time course analysis showed that the levels of pattern recognition receptors and the phosphorylated forms of NF-κB and IRF3 peaked 48 h after RV 16 infection and 24 h after poly (I: C) treatment in both groups of epithelial cells and activated without delay in inflammatory epithelial cells." (PMID 36341332, 2022). "We found in PMA differentiated THP1 cells, which is considered to be M0 phenotype and is prone towards proinflammatory commitment, wildtype MYXV infection still suppressed overall levels of phosphorylated IRF3 at this time, while ΔM062R infection continued to show increased phosphorylated IRF3." (PMID 36103568, 2022). "Moreover, the PB protein Lsm14A has been shown to bind to viral RNA/DNA after infection-induced PB disassembly to promote IRF3 activation and IFN-β production." (PMID 35998203, 2022). "Taken together, these data indicate that the expression of TLR3, RIG-I, MDA5, and the phosphorylated forms of NF-κB and IRF3 are normally induced in inflammatory epithelial cells derived from patients with CRSwNP when infected with RV 16 infection or treated with poly (I: C)." (PMID 36341332, 2022). "Additionally, during HSV-1 F and KOS Δ21 infections, translocation of IRF-3 to infected nuclei occurred 2 hours earlier than their respective WT infections." (PMID 36374856, 2022). "By contrast, all of the Ifih1−/−Sting1gt/gt or Irf3−/− mice died at day 7–9 post-infection." (PMID 35351885, 2022).
infection (continued). "We observed phosphorylation of IRF3 in wildtype MYXV infection of macrophage-like cells likely due to the RIG-I-associated mechanism as previously reported, albeit at a much lower level than that stimulated by ΔM062R infection." (PMID 36103568, 2022). "MVA∆C7L infection of BMDCs induced higher levels of phosphorylation of IRF3 compared with MVA." (PMID 35351885, 2022). "After infection for 8 h, SeV could induce the phosphorylation of IRF3 Ser396, and this was obviously enhanced when the infection reached 16 h." (PMID 35196784, 2022). "Notably, the activity of mouse Yap was dramatically stimulated in the lungs 2 to 4 days post-infection, which was accompanied by activation of Irf3." (PMID 35503798, 2022). "Interestingly, OROV-infected IFN regulatory factor 5 KO (IRF5−/−) mice exhibited signs of hepatic injury early in the infection, increased viral titers in the spinal cord, and delayed death relative to IRF3−/− IRF7−/− DKO mice." (PMID 35301331, 2022). "Collectively, these results indicate that during HCEC infection with HSV-1, RNF5 could aggravate the infection by inhibiting the STING/IRF3 signaling pathway and reducing the expression of IFN-β." (PMID 35992663, 2022). "NS1 could trigger OTUB1 proteasomal degradation at the later stages of infection, leading to the inhibition of IRF3 and NF-κB activation, and thus preventing the antiviral response." (PMID 34835115, 2021). "Upon SeV or EMCV infection, macrophages or MEFs with the deficiency of USP18 showed impaired phosphorylation of TBK1 and IRF3, expression of Ifnb and Ccl5, and production of IFN-β, indicating that USP18 plays a positive role in regulating viral-induced type-I interferon response." (PMID 34016972, 2021). "Additionally, arginine methylation of hnRNPA1/B2 triggers its export to the cytoplasm where it activates TBK1/IRF3 signaling following infection with a DNA virus." (PMID 34305890, 2021). "Using the production of IFN-β mRNA and phosphorylation of IRF-3 in infected cells as markers for an activated RIG-I signal we detected a first increase in IFN-β transcription 5 hours post infection (hpi) - visible only on an x-axis with logarithmic scale (data not shown)." (PMID 33995343, 2021). "However, in THP-1 cells (a human monocyte cell line broadly used for immune assay experiments) we detected increasing amounts of p-IRF3 upon infection with viruses harboring accumulating inactivation in genes interfering with the IRF3 pathway." (PMID 34553028, 2021). "We detected a significant increase in IRF3 levels at all MOIs after 48 h and 72 h infection." (PMID 34926703, 2021). "Indeed, it has been shown that H3N2 and H2N2 IAV strains infections lead to a high IRF3 and IFNβ activation, despite a proper interaction between NS1 and TRIM25." (PMID 34835115, 2021). "Moreover, it has been shown that TRIM26 interacts with IRF3 in the nucleus after infection with Sendai virus (SeV) in macrophages." (PMID 33419081, 2021). "In addition, knockout of either IRF3 or IRF7 indicated a crucial role of IRF7 as the driver of IFNβ expression in an infection model of DENV." (PMID 33498715, 2021). "IRF3 gene expression was increased at the peak only after infection with HEV3- JN837481." (PMID 32731452, 2020). "This suggested that infection with vSlfn mutant viruses was sufficient to trigger IRF3 activation." (PMID 32948585, 2020). "Further, we will inspect the regulatory mechanisms of these steps imposed by the host cell and present the manifold strategies viruses have evolved to intervene with IFNβ transcription downstream of IRF3 activation in order to secure establishment of a productive infection." (PMID 32645843, 2020). "However, premature vesicle disruption allowed for robust sensing of DNA delivered by R302/5A infection as measured by IRF3 phosphorylation, most prominently at 4 hr and 8 hr post-infection." (PMID 33253291, 2020).